CDC42 (cell division cycle 42)
Diseases named in the same sentence as CDC42 in open-access papers (continued):
Sharing a sentence is not in itself a finding about the gene and the disease.
Stroke (8 papers, 2011 to 2024). Sudden impairment of blood flow to a part of the brain due to occlusion or rupture of an artery to the brain. "Lower CDC42 was associated to lower occurrence of anxiety (P=0.002), depression (P=0.001), and cognitive impairment (P=0.036) in stroke patients." (PMID 37703110, 2023). "This study aimed to assess the correlation between blood CDC42 and Th cells, and their association with mental issues in stroke patients." (PMID 37703110, 2023). "In our study, low CDC42 was associated with the occurrence of anxiety and depression to some extent in stroke patients." (PMID 37703110, 2023). "In conclusion, CDC42 was negatively correlated with Th17 cells, and both were associated with psychiatric disorders in stroke patients, indicating that their monitoring may contribute to the management of mental and cognitive problems after stroke." (PMID 37703110, 2023). "For example, in one previous study, serum CDC42 is reduced in stroke patients compared to healthy individuals." (PMID 38476381, 2024). "Our results showed that plasma CDC42 levels were lower in the hyperacute phase of stroke than in the control group." (PMID 36831829, 2023). "CDC42 was positively associated with MMSE score (r=0.227, P<0.001), and low CDC42 was correlated to the occurrence of cognitive impairment in stroke patients (P=0.036)." (PMID 37703110, 2023). "In stroke patients with recurrence experience, low CDC42 was correlated with the occurrence of anxiety (P=0.011) and cognitive impairment (P=0.039), while it was not correlated with the occurrence of depression (P=0.088)." (PMID 37703110, 2023). "In conclusion, our findings suggest that SCH enhanced NPCs proliferation and differentiation possible by Cdc42 to regulated cytoskeletal rearrangement and polarization of cells, which provides new hope for the late recovery of stroke." (PMID 34946548, 2021). "Similarly, our study revealed that CDC42 was positively associated with MMSE score, and low CDC42 was related to the occurrence of cognitive impairment in stroke patients." (PMID 37703110, 2023). "Furthermore, CDC42 showed a good value to distinguish stroke patients from controls with area under curve of 0.850 (95% confidence interval: 0.801-0.900)." (PMID 37703110, 2023). "CDC42 was reduced in stroke patients compared with controls (P<0.001)." (PMID 37703110, 2023). "In stroke patients without recurrence experience, low CDC42 was associated with the occurrence of anxiety (P=0.038) and depression (P=0.004), while it was not related to the occurrence of cognitive impairment (P=0.293)." (PMID 37703110, 2023). "Interestingly, CDC42 was negatively associated with HADS-anxiety (P<0.001) and HADS-depression scores (P=0.034) and positively associated with MMSE score (P<0.001) in stroke patients." (PMID 37703110, 2023). "In addition to CDC42, the association of CD4+ T cells with mental health and cognitive function is also a key issue in stroke patients' management." (PMID 37703110, 2023). "CDC42 was negatively correlated with the National Institutes of Health Stroke Scale (NIHSS) score (p < 0.001), whereas, in patients with AIS (all p < 0.050), it was positively associated with Th2 cells and IL-4 but negatively correlated with Th17 cells and IL-17A." (PMID 35547377, 2022). "Interestingly, the multivariate logistics regression models revealed that higher CDC42 was independently associated with lower risk of anxiety (odds ratio=0.401, P=0.043), but not with depression or cognitive impairment in stroke patients." (PMID 37703110, 2023). "Furthermore, CDC42 was negatively correlated to Th17 cells (r=-0.303, P<0.001) in stroke patients." (PMID 37703110, 2023). "CDC42 was negatively correlated with HADS-A score (r=-0.258, P<0.001), and low CDC42 was correlated with the occurrence of anxiety in stroke patients (P=0.002)." (PMID 37703110, 2023).
Stroke (continued). "CDC42 was inversely correlated with HADS-D score (r=-0.131, P=0.034), and low CDC42 was correlated with the occurrence of depression in stroke patients (P=0.001)." (PMID 37703110, 2023). "In a mouse stroke model, CDC42, not RHOA, was the main protein related to cytoskeleton formation and cell polarization." (PMID 36831829, 2023). "Nevertheless, the relationship between CDC42 and mental health in stroke patients has not been reported." (PMID 37703110, 2023). "Therefore, this study aimed to evaluate the relationship between CDC42 and CD4+ T cells, as well as their correlations with anxiety, depression, and cognitive impairment in stroke patients." (PMID 37703110, 2023). "Third, this study only evaluated the clinical role of CDC42 in patients with AIS but lacked the exploration of other stroke types (such as hemorrhagic stroke)." (PMID 35547377, 2022). "As peripheral blood markers of the ischemic penumbra, the expression patterns of CDC42 and RHOA in nonhuman primate stroke models differ from those in rats that we previously reported." (PMID 36831829, 2023). "In the current study, we evaluated whether the levels of CDC42 and RHOA in plasma are related to DWI-FLAIR mismatch in the hyperacute phase of stroke in nonhuman primates." (PMID 36831829, 2023).
Thrombocytopenia (8 papers, 2011 to 2025). A reduction in the number of circulating thrombocytes. "Genetic variants in cell division cycle 42 (CDC42) can manifest with dysmorphic features, autoinflammation, hemophagocytic lymphohistiocytosis, and thrombocytopenia, whereas defective thymopoiesis is a rare disease manifestation." (PMID 37581646, 2023). "Previous studies have reported that de novo missense variants in the CDC42 gene can often result in a number of clinical manifestations, including developmental delay, facial dysmorphism, recurrent infections, and thrombocytopenia." (PMID 33672558, 2021). "In the proband studied here, in which a novel, de novo missense p.P34Q mutation in the CDC42 gene was identified for the first time, being characterized by poor wound healing, pancytopenia, recurrent infections, and thrombocytopenia." (PMID 33672558, 2021). "Our findings that inducible gene targeting of Cdc42 results in a significant thrombocytopenia and prolonged tail bleeding times in Cdc42-deficient mice demonstrate that Cdc42 is essential for normal platelet function." (PMID 21789221, 2011). "Since Wiskott-Aldridge Syndrome Protein (WASP) is regulated by Cdc42, deficiency of Cdc42 may be involved in thrombocytopenia." (PMID 21789221, 2011). "Technical difficulties in reintroducing Cdc42 mutants (e.g. defective in WASP binding) to platelets pose another challenge for demonstrating a causal relationship between Cdc42 deficiency, defective WASP activation and thrombocytopenia." (PMID 21789221, 2011). "Importantly, Cdc42−/− MKs displayed only partially reduced membrane invaginations, indicating that the thrombocytopenia in these mice was not solely the result of a lack of intracellular membranes." (PMID 28643773, 2017).
Anxiety (7 papers, 2014 to 2023). Intense feelings of nervousness, tension, or panic often arise in response to interpersonal stresses. "Blood CDC42 and Th17 cells were correlated, and both of them were linked to the risk of anxiety, depression, and cognitive impairment." (PMID 37703110, 2023). "One study reported that inhibition of brain CDC42 activity causes anxiety in mice." (PMID 37703110, 2023). "One study indicates that inhibition of CDC42 increases anxiety in mice." (PMID 37703110, 2023). "Altering the ratio of Cdc42 isoforms leads to increased anxiety in mice." (PMID 30590745, 2019). "Because our Cdc42f/f: Camk2a-Cre mice showed defects in the synaptic plasticity and reduction of dendritic spines in the hippocampus, we hypothesized the Cdc42 cKO mice might exhibit an anxiety phenotype." (PMID 25006034, 2014). "Together these data confirmed that the Cdc42 cKO mice show normal anxiety levels." (PMID 25006034, 2014). "Similarly, structural and functional plasticity in hippocampal neurons was abolished in forebrain-specific, conditional Cdc42 knockout animals, which was accompanied by deficits in remote memory recall, whereas working memory, anxiety levels and locomotor activities were unaltered." (PMID 34360003, 2021).
esophageal squamous cell carcinoma (7 papers, 2015 to 2022). Esophageal squamous cell carcinoma (ESCC) is a type of esophageal carcinoma (EC) that can affect any part of the esophagus, but is usually located in the upper or middle third. "CDC42 is connected with the tumorigenesis and promotion of esophageal squamous cell carcinoma (ESCC)." (PMID 34771549, 2021). "Inhibition of TUG1 can inhibit the proliferation and invasion of cells by up-regulating miR-498 and down-regulating CDC42 in esophageal squamous cell carcinoma cells." (PMID 32391554, 2020). "A previous study has indicated that miR-195 was downregulated in esophageal squamous cell carcinoma and inhibited cell proliferation and invasion by targeting Cdc42." (PMID 28487599, 2017).
Hyperglycemia (7 papers, 2019 to 2026). An increased concentration of glucose in the blood. "Therefore, an indirect effect of Cdc42 on leptin levels is possible through renal dysfunction with Cdc42 activation in podocytes and renal vascular cells caused by hyperglycemia." (PMID 38068822, 2023). "SRGAP2a inactivates RhoA/Cdc42 to suppress podocyte motility, maintaining structure and preventing injury under hyperglycemia or TGF-β stimulation." (PMID 41009556, 2025). "The results demonstrate that the Cdc42 plays an important role in the process of hyperglycemia-induced HUVECs dysfunctions by changing the elastic modulus of HUVECs." (PMID 38343879, 2024). "The rearrangement of the cytoskeleton induced by hyperglycemia through Cdc42 was found to be one of the pathways for the alteration of the cell stiffness and the subsequent cell dysfunctions." (PMID 38343879, 2024). "In recent years, study showed that expression of constitutively active Cdc42 interfered with β cell delamination and differentiation leading to hyperglycemia." (PMID 30621321, 2019). "Hyperglycemia-induced overexpression of cdc42 may be the reason for the polymerization of G-actin into F-actin, remodeling the cell structure, increasing the stiffness of the cytoskeleton and then impeding cell migration." (PMID 38343879, 2024). "Besides, several studies have demonstrated Cdc42 as participating in the pathogenesis of IR and DN and even contributing to promote cancer cell proliferation, survival, invasion, migration, and metastasis under hyperglycemia." (PMID 30621321, 2019). "Therefore, our study might give some hints to the detailed relationship between hyperglycemia and tissue regeneration: under HG conditions, the stress fiber assembly of HUVECs was significantly changed and led to the stiffen of HUVECs via regulating the cdc42 expression." (PMID 38343879, 2024).
Parkinson disease (7 papers, 2015 to 2025). A progressive degenerative disorder of the central nervous system characterized by loss of dopamine producing neurons in the substantia nigra and the presence of Lewy bodies in the substantia nigra and locus coeruleus. "CDC42 which is a member of the Rho GTPase family is a target of miR-326, and CDC42 dysregulation is linked to neuronal diseases such as Alzheimer’s and Parkinson’s disease." (PMID 33240875, 2020). "In a mouse model of Parkinson’s disease, a CDC42 inhibitor inhibited microglial reaction and protected neurons from phagocytosis." (PMID 41169985, 2025). "In summary, our current observations suggest a novel mechanism in which Cdc42 signaling in the CPu, regulated by dopamine D2R, contributes to deficits in spine abnormities and motor coordination and cognition, characteristic of Parkinson's disease." (PMID 35415964, 2022). "Utilizing conditional dopamine D1 receptor or D2 receptor knockout mice, our results demonstrate that impaired Cdc42 signaling, regulated by dopamine D2 receptor but not D1 receptor, plays an important role in spine loss and behavioral deficits in a Parkinson's disease mouse model." (PMID 35415964, 2022). "Thus, we hypothesized that Cdc42 may be crucially involved in Parkinson's disease‐like behavior." (PMID 35415964, 2022).
Sepsis (7 papers, 2013 to 2025). Sepsis is defined as life-threatening organ dysfunction caused by a dysregulated host response to infection. "Animal studies have shown that free heme interferes with DOCK8-mediated Cdc42 activation, inducing extensive actin cytoskeleton changes and strongly suppresses phagocyte functions predisposing to bacterial dissemination and sepsis." (PMID 35386989, 2021). "Severe systemic infections including septicemia, and disseminated intravascular coagulation emerged as the predominant infectious complications of CDC42 GTPase patients compared to the RAC2 GTPase group." (PMID 40860338, 2025). "Pathways that are modulated during sepsis such as Cdc42 signaling, phospholipase C signaling, interleukin 17 (IL-17) signaling, protein ubiquitination pathway, glucocorticoid receptor and p38 MAPK signaling were observed." (PMID 26047321, 2015). "Moreover, drugs with direct effects on Rho proteins, including but not limited to RhoA, Rac1, and Cdc42, remain to be further explored in sepsis." (PMID 34440613, 2021).
endometrial cancer (6 papers, 2018 to 2023). Primary or metastatic malignant neoplasm involving the endometrium (mucous membrane that lines the endometrial cavity). "Only rs10917151 (CDC42/WNT4) associates with endometrial cancer (P = 4.5 × 10−4, logistic regression, OR 1.14) after correcting for the number of tests (P = 0.05/21 = 0.0024)." (PMID 30194396, 2018). "The top incidences of Cdc42 amplification (cBioPortal) are in endometrial carcinoma, bladder urothelial carcinoma, sarcoma and ovarian epithelial tumours, and suggest an increase in protein levels and therefore signalling." (PMID 34196668, 2021). "Interestingly, 29 of the 32 Cdc42 effectors have endometrial carcinoma in the top five cancer types where they are found altered, suggesting understanding and potentially targeting Cdc42 signalling in this cancer could have therapeutic benefit." (PMID 34196668, 2021).
Insulin resistance (6 papers, 2019 to 2023). Increased resistance towards insulin, that is, diminished effectiveness of insulin in reducing blood glucose levels. "A recent study showed that increased Cdc42 activity in hepatocytes associated with insulin resistance leads to the suppression of lipophagy, a type of autophagy." (PMID 38068822, 2023). "Dysregulation of Cdc42, whether induced by external or internal factors, appears to be an important contributor to the development of leptin and insulin resistance." (PMID 38068822, 2023). "In Western blotting analysis using N2a cells under insulin resistance, we found that phosphorylation of RAC/Cdc42 was commonly decreased under both insulin-resistant conditions." (PMID 35055191, 2022). "From the aspect of decline of insulin secretion, the reduction of Cdc42 suppresses the activity of PAK-1 and may promote insulin resistance." (PMID 30621321, 2019).
liver fibrosis (6 papers, 2019 to 2024). "The effective reduction of bile acids notably improved the serological indices, and dramatically reduced liver fibrosis and cholangiocyte proliferation in the K19-CreERT:Cdc42-/- mice." (PMID 34158849, 2021). "Ask1 inhibition reduces kidney and liver fibrosis Cdc42 and Rac1 mediate JNK activation in the context of polycystin overexpression in cells and activate Mlk2 and Mlk3 However, in our model, Ask1 deletion or double deletion of Mlk2 and Mlk3 did not reduce cystic burden in Pkd2 mutants." (PMID 34962918, 2021). "In addition to regulating profibrogenic genes, 3D-Exo also significantly reduced gene expression of the common markers of cell proliferation (CYCLIND, RAC1 and CDC42) in activated LX2 cells, which are usually upregulated in activated stellate cells during liver fibrosis." (PMID 34930304, 2021).
metastatic cancer (6 papers, 2015 to 2023). A carcinoma which has spread from the original site of growth to another anatomic site. "Rac/Cdc42 GEFs are activated by a myriad of oncogenic cell surface receptors, such as growth factor receptors, G-protein coupled receptors, cytokine receptors, and integrins; consequently, a number of Rac/Cdc42 GEFs have been implicated in metastatic cancer." (PMID 32322580, 2020). "In conclusion, the plethora of compelling data discussed in this review realizes the promise of Rac/Cdc42 inhibitors as viable therapeutics for metastatic cancer, and we look forward to their routine use in standard cancer care." (PMID 32322580, 2020). "The higher concentration of EH not only inhibit Rac1 but also Rac3 and Cdc42 in the MDA-MB-435 metastatic cancer cells." (PMID 26766136, 2016). "The inhibitor of Rac/Cdc42 significantly decreased the activity of STAT3 in metastatic cancer." (PMID 37752569, 2023). "Herein, we focus on the role of oncogenic Rac/Cdc42 GEFs and discuss the recent advancements in the development of Rac and Cdc42 GEF-interacting inhibitors as targeted therapy for metastatic cancer, as well as their potential for overcoming cancer therapy resistance." (PMID 32322580, 2020). "Our data using a trastuzumab resistant HER2 type metastatic cancer have demonstrated the efficacy of Rac/Cdc42 inhibitors to block metastatic cancer cell functions, tumor growth, and metastasis; thus highlighting the utility of Rac inhibitors to overcome trastuzumab resistance." (PMID 32322580, 2020). "Hence, inhibiting GEF-mediated Rac/Cdc42 activation represents a promising strategy for targeted metastatic cancer therapy." (PMID 32322580, 2020). "Herein, we discuss the relevance of Rac/Cdc42 GEFs in metastatic cancer cell signaling in the context of the GEF interaction inhibitors that target Rac and Cdc42 activation." (PMID 32322580, 2020). "Not surprisingly, Rac1 and Cdc42 activity are often increased in highly motile cells and metastatic cancer." (PMID 25649192, 2015). "So far, no Rac/Cdc42 inhibitors have received FDA approval for clinical trials; however, burgeoning evidence has positioned Rac and Cdc42 as ideal targets for anti-metastatic cancer therapy." (PMID 32322580, 2020).
acute myeloid leukemia (5 papers, 2019 to 2025). Acute myeloid leukemia (AML) is a group of neoplasms arising from precursor cells committed to the myeloid cell-line differentiation. "The identified p.P34Q mutation in the CDC42 gene was previously reported in a young male patient presenting with an acute myeloid leukaemia (COSMIC database, sample ID: COSS2810409)." (PMID 33672558, 2021). "In the context of acute myeloid leukemia (AML), the loss of CDC42 disrupts cell polarity and division asymmetry, leading to the alteration of leukemia-initiating cell fate in differentiation therapy." (PMID 40868343, 2025). "In human acute myeloid leukemia (AML), transformation by mutant CBL depends on functional expression of Cdc42 and increased glucose metabolism." (PMID 30621321, 2019).
diabetic retinopathy (5 papers, 2023 to 2025). "In parallel, Huang and Zhou combined integrative bioinformatics with in vivo validation to uncover critical regulators such as CD44 and CDC42 in the context of diabetic retinopathy, underscoring the translational potential of network-based approaches in ocular disease research." (PMID 40548296, 2025). "have pinpointed six significant genes (CD44, CDC42, TIMP1, BMP7, RHOC, FLT1) as crucial for diabetic retinopathy through advanced bioinformatics analysis coupled with in vivo validation." (PMID 38605967, 2024).